MYCN (MYCN proto-oncogene, bHLH transcription factor)
Diseases named in the same sentence as MYCN in open-access papers (continued):
Sharing a sentence is not in itself a finding about the gene and the disease.
retinoblastoma (continued). "MYCN-amplified tumors together with other retinoblastoma tumors in branch 1 belonged to the category of samples with a continuously lower photoreceptorness score." (PMID 36245757, 2022). "In total, 5 retinoblastomas displayed high-level MYCN amplification, with 3 being RB1+/+, 1 being RB1+/–, and 1 being RB1–/–." (PMID 36245757, 2022). "Integrated analysis, based on gene expression, methylation, and methylation-expression correlations, was performed to identify distinct molecular components of MYCN-amplified RB1-proficient retinoblastomas compared with other retinoblastoma subtypes." (PMID 36245757, 2022). "Various studies have highlighted MYCN expression in Rb tumors, while we show the presence of the differential expression of MYCN in Rb tumor subtypes." (PMID 35626705, 2022). "A large number of genes (n = 3155) were identified with distinct expression patterns in MYCN-amplified RB1-proficient retinoblastomas." (PMID 36245757, 2022). "The present analysis reconfirmed the clustering of MYCN-amplified RB1-proficient wild-type tumors within a retinoblastoma subbranch characterized by lower photoreceptorness." (PMID 36245757, 2022). "In this study, we explored unique transcriptomic and epigenomic features of MYCN-amplified RB1-proficient retinoblastomas compared with other retinoblastomas." (PMID 36245757, 2022). "Our data show that hypermethylation in MYCN-amplified samples is the most important epigenetic event inducing gene expression differences between MYCNARB1PRO retinoblastoma and the other retinoblastomas." (PMID 36245757, 2022). "In the current study, we have studied the expression of MYCN in retinoblastoma primary tumor tissues and compared it with various histological and clinical parameters." (PMID 34680394, 2021). "In the series of 102 retinoblastomas, tumors with MYCN amplification accounted for 17% of subtype 2 tumors." (PMID 34552068, 2021). "A small minority of retinoblastoma cases (<1%) have been found to have two active copies of the RB1 gene but somatic MYCN amplification." (PMID 33805427, 2021). "In contrast, MYCN was highly expressed in c5 (retinoblastoma cells) a gene played crucial roles in tumour cell proliferation that was consistent with previous study." (PMID 34815392, 2021). "MYCN gain/amplification occurs in approximately 8% of retinoblastoma and is included in the most common focal genomic aberration." (PMID 32824373, 2020). "Lymph node dissemination was previously reported in two transgenic mice models with RB1−/− retinoblastoma and MYCN amplification." (PMID 32971811, 2020). "Here, we show that MYCN overexpression upregulates MDM2 in a fetal retina model that recapitulates features of human MYCN-amplified retinoblastoma." (PMID 33425720, 2020). "MYCNOS (MYCN opposite strand) is co-amplified with MYCN in pediatric cancers, including retinoblastoma." (PMID 33270844, 2020). "In retinoblastomas, MYCN amplification is present in <5% of patients, and MYCN gain is associated with poor prognosis." (PMID 33628735, 2020). "In oncogenic-driven retinoblastoma, MYCN is focally amplified with >28 copies, spanning 1 to 5 Mb and encompassing neighboring genes." (PMID 33270844, 2020). "A copy number of MYCN greater than 28 is considered high amplification and is associated with RB1+/+ or RB1+/− retinoblastoma." (PMID 32824373, 2020). "Retinoblastoma (RB) is an inherited retinal disorder (IRD) caused by the mutation in the RB1 gene or, rarely, by alterations in the MYCN gene." (PMID 31835688, 2019). "The missing events were a high-level episomal MYCN amplification in retinoblastoma SJRB051 and an FXR1–BRAF fusion in low-grade glioma SJLGG026." (PMID 30262806, 2018). "We compared the relative levels of expression of SKP2, p27, pRb, and ppRb proteins in four MYCN‐amplified and one MYCN‐low retinoblastomas by immunohistochemistry (IHC) staining of tumor sections with antibodies specific for these proteins." (PMID 28211617, 2017).
retinoblastoma (continued). "Genome architecture, including whole genome chromosome copy number gains and losses, were determined for 38 retinoblastomas: 14 MYCN‐amplified and 24 MYCN‐low tumors." (PMID 28211617, 2017). "MDM2 increases MYCN transcription and translation and thus sustain the high levels of MYCN essential for increased retinoblastoma proliferation." (PMID 28358317, 2017). "In a recently published paper an aurora kinase A inhibitor was successfully used to reduce MYCN protein levels in a retinoblastoma cell line." (PMID 29124525, 2017). "In this manuscript, we investigated the characteristics of MYCN‐amplified sporadic unilateral retinoblastoma and the mechanisms of inactivation of the RB1 gene in these tumors." (PMID 28211617, 2017). "In mice, MYCN overexpression alone was insufficient to drive retinoblastoma development, however, tumors formed when overexpression was combined with RB1 deletion." (PMID 29124525, 2017). "We identified 18 of 245 retinoblastomas (7%) with a high MYCN copy number between 29 and 110 copies." (PMID 28211617, 2017). "We next estimated the copy number status of the MYCN oncogene in the 245 retinoblastomas, which ranged from 1 to 128 copies." (PMID 28211617, 2017). "This difference in the number of MYCN‐amplified retinoblastomas carrying two, one, or zero RB1 mutations (eight, four, and six, respectively) compared to MYCN‐low tumors (195, 25, and seven, respectively) was significant (P < 0.001)." (PMID 28211617, 2017). "Gallie and colleagues discovered that a small proportion of retinoblastomas lack RB1 mutations and had MYCN amplification." (PMID 24509483, 2014). "Another recurrent focal amplification found in ~9% of retinoblastomas is a region of the genome on chromosome 2p spanning the MYCN oncogene." (PMID 24509483, 2014). "The possibility of a primary role of MYCN in retinoblastoma tumorigenesis was first suggested in 1984 when Lee and colleagues described retinoblastomas with MYCN amplifications." (PMID 24509483, 2014). "It has been previously reported that a small proportion (1.5%) of retinoblastomas with MYCN amplification express wild type RB1." (PMID 24509483, 2014). "The MYCN gene is the only known oncogene found to be focally recurrently amplified in human retinoblastomas in about 10% of cases." (PMID 23765217, 2013). "MYCN amplification without concurrent RB1 mutations characterizes a rare yet highly aggressive subtype of retinoblastoma; however, its precise developmental origins and therapeutic vulnerabilities remain incompletely understood." (PMID 40943594, 2025). "However, while a small group of retinoblastomas with intact, phosphorylatable pRB, is driven by MYCN amplifications, a major subset of pineoblastomas is induced by amplifications or stabilization of cMYC." (PMID 40075567, 2025). "These MYCN-amplified retinoblastomas exhibit distinct molecular signatures and demonstrate a clinically aggressive phenotype, characterized by rapid tumor growth, earlier age of onset typically within the first year of life, increased metastatic risk, and poor cellular differentiation." (PMID 40943594, 2025). "In rare cases, it could also be due to retinoblastoma with MYCN amplification with wild-type RB1 (MYCNARB1+/+)." (PMID 40338593, 2025). "The differences between these studies and our findings reflect the inherent diversity and complexity of retinoblastoma cellular origins, suggesting that MYCN-driven retinoblastomas may originate from multiple retinal progenitor or precursor populations." (PMID 40943594, 2025). "Understanding how MYCN hijacks retinal developmental programs and interacts with diverse signaling pathways and transcriptional networks will be essential for the discovery of novel therapeutic targets and intervention strategies in retinoblastoma." (PMID 40943594, 2025). "The relationship between BRAF mutations and RB in retinoblastoma is not as well documented as other genetic alterations like RB1 mutations or MYCN amplification." (PMID 40317918, 2025).
retinoblastoma (continued). "Although our present data do not directly document apoptotic events, this explanation remains biologically plausible, and further experimental studies will be necessary to clarify the contribution of apoptosis resistance to the initiation and progression of MYCN-driven retinoblastoma." (PMID 40943594, 2025). "Collectively, these findings demonstrate that MYCN-overexpressing retinoblastoma organoids generate stable cell lines capable of robust tumor formation in vivo, closely resembling the key histopathological and molecular features of human MYCN-amplified retinoblastoma." (PMID 40943594, 2025). "Moreover, lentivirus-mediated over-expression of MYCN in human RB1-proficient foetal retina also induces tumorigenic growth resembling retinoblastoma." (PMID 37606819, 2024). "We applied the MYCN-RB signature to our RNA sequencing dataset from 52 primary retinoblastomas." (PMID 39079981, 2024). "The MYCN-RB signature identified cluster C retinoblastomas and can be used to identify retinoblastoma cases that may benefit from MYCN-directed therapies." (PMID 39079981, 2024). "Contrary to human cases where MYCN amplification drives retinoblastoma without RB1 mutation, in a mouse model, overexpressing MYCN in retinal cells with wildtype pRB did not induce tumor formation." (PMID 39000021, 2024). "The differentiation observed upon MYCN knockdown could hint that subtype 1 retinoblastoma is able to transition to subtype 2-MYCN (cluster C) retinoblastoma upon MYCN activation." (PMID 39079981, 2024). "Likewise, the expression of genes descriptive of the photoreceptor-rich retinoblastoma in the cell line models after MYCN knockdown shows that MYCN is involved in maintaining undifferentiated state of retinoblastoma cells." (PMID 39079981, 2024). "Analyzing recently published data on genomic alterations related to annotated genes for a 102-cohort, reveals that loss of chr16q22.2 (containing DHODH) is amongst the most frequent alterations in retinoblastoma and comparable to MYCN and MDM4 gain/amplification." (PMID 38332874, 2024). "We also defined and validated a MYCN-RB gene signature to identify retinoblastomas that could benefit from MYCN-targeting treatment." (PMID 39079981, 2024). "DNA methylation analysis identifies a MYCN-driven subgroup of aggressive retinoblastoma that may benefit from MYCN-targeted therapy." (PMID 39079981, 2024). "The MYCN-RB gene signature generated from the cell models better identifies MYCN-driven retinoblastoma than MYCN amplification and can identify cases that may benefit from MYCN-targeted therapy." (PMID 39079981, 2024). "Targeting key MYCN down-stream effectors such as elevated E2fs may be a feasible way to treat those cancers including retinoblastoma with MYCNA." (PMID 37606819, 2024). "The DMC cells can be established with high frequency (100% of successful in ovo electroporations) from dissected embryonic retinal tumours and the MYCN tumour cells grow in suspension with concomitant cell death similar to patient derived MYCN-retinoblastoma lines." (PMID 37606819, 2024). "MYCN drives tumor progression in a molecularly defined retinoblastoma subgroup, and inhibiting MYCN activity could restore a more differentiated and less aggressive tumor biology." (PMID 39079981, 2024). "Analysis of cfRNA from aqueous humor could in the future also allow to identify MYCN-RB signature in retinoblastoma treated with eye-preserving therapy." (PMID 39079981, 2024). "Such phenotype is consistent with the phenotype of retinoblastoma with MYCN amplifications." (PMID 37606819, 2024). "MYCN knockdown upregulated genes descriptive of the photoreceptor-rich cluster A retinoblastoma and downregulated genes representative of the photoreceptor-poor, undifferentiated and cluster C retinoblastoma in cell models." (PMID 39079981, 2024). "Moreover, retinoblastoma can be driven by amplification of MYCN for a certain gain, such as 17q and 18q." (PMID 38540335, 2024).
retinoblastoma (continued). "Earlier studies have shown that glucose metabolism is highly regulated by MYCN in retinoblastoma." (PMID 37046804, 2023). "Indeed, MYCN amplification has been found as a significant prognostic marker in a small sub-cohort of retinoblastomas carrying functional wt copies of the RB1 gene." (PMID 36982482, 2023). "Again, MYCN-amplified retinoblastomas classified in the undifferentiated group." (PMID 36245757, 2022). "The fact that we find downregulation of genes that are important for proliferation in MYCN-amplified RB1-proficient retinoblastoma may initially seem counterintuitive." (PMID 36245757, 2022). "Interestingly, the two MYCN-amplified retinoblastomas that were included in this cohort clustered together with the undifferentiated RB1–/– retinoblastomas." (PMID 36245757, 2022). "Our results indicate that MYCN over-expression is sufficient in inducing tumorigenic growth when occurring in the fate-restricted cPR/HC progenitor in the chicken retina and that the growth develops into less differentiated retinoblastoma." (PMID 35729105, 2022). "The upregulation of translation and mRNA synthesis in MYCN-amplified RB1-proficient retinoblastomas may be the direct outcome of MYCN overexpression." (PMID 36245757, 2022). "Retinoblastoma widely expresses the ganglioside GD2 even in pre-treated chemo-refractory cases with MYCN amplification, suggesting that anti-GD2 monoclonal antibodies may be effective." (PMID 35433448, 2022). "GD2 is widely expressed in retinoblastoma, and MYCN amplification in pretreated chemo-refractory cases, suggesting that for treatment of RB, anti-GD2 monoclonal antibodies may be effective." (PMID 36132125, 2022). "In addition, cilia assembly was also identified as a potential differential regulated pathway in MYCN-amplified RB1-proficient retinoblastomas compared with the rest of the cohort." (PMID 36245757, 2022). "The present study dove deeper into the biology of the MYCN retinoblastoma subtype by correlating information of different molecular levels, defining MYCN-amplified RB1-proficient retinoblastoma as a unique retinoblastoma subtype with a distinct molecular background." (PMID 36245757, 2022). "We also wanted to determine whether MYCN over-expression can generate retinoblastoma with high frequency in RB1-proficient retina." (PMID 35729105, 2022). "This gene set can give insight into the biology of MYCN-amplified retinoblastomas and may help us to understand the more aggressive clinical behavior." (PMID 36245757, 2022). "The MYCN amplification status was analyzed, because it was published that in a subgroup of retinoblastoma, no RB1 mutation was found, but instead a MYCN amplification." (PMID 36497295, 2022). "Besides RB1, there is another gene, MYCN, which is the most commonly amplified gene found in retinoblastoma." (PMID 34639028, 2021). "However, WGS allowed us to look at the full compendium of mutations in our cohort of retinoblastomas and suggests that driver mutations beyond RB1, MYCN BCOR and recurrent copy number changes on 1q, 2p, 6p, and 16q are rare." (PMID 33670346, 2021). "Furthermore, we have explored the possibility of targeting MYCN in retinoblastoma using small molecule inhibitors and shRNA approaches." (PMID 34680394, 2021). "The numbers in both studies are small and further expression studies on larger cohorts of tumours are warranted to confirm whether MYCN over expression is a common feature of retinoblastoma." (PMID 33670346, 2021). "In addition to mutations, three patients exhibited MYCN amplification, in the presence of an RB1 mutation, which has been shown previously to be prevalent in retinoblastoma." (PMID 33466343, 2021). "Importantly, there were also copy number gains in MDM4 and MYCN which are common in retinoblastomas." (PMID 34315877, 2021). "For example, MYCN, has been shown to be amplified and overexpressed in retinoblastoma." (PMID 34680394, 2021).
retinoblastoma (continued). "This conflicts with human tumorigenesis where high MYCN amplification is proposed as a driver in a rare form of retinoblastoma without RB1 mutation." (PMID 32824373, 2020). "A limitation of this study is the small sample size and that the sample included extremely rare cases of MYCN-amplified retinoblastoma without RB1 mutation." (PMID 33270844, 2020). "Our findings suggest that MYCNOS1 knockdown is a potential therapeutic strategy for MYCN-amplified retinoblastoma without RB1 mutation." (PMID 33270844, 2020). "Together, these results suggest that MYCNOS1 maintained the cone signature in MYCN-amplified retinoblastoma without RB1 mutation." (PMID 33270844, 2020). "Our finding that MYCN promotes MDM2 expression in the retinoblastoma cell of origin and that MDM2 promotes MYCN expression in retinoblastoma cells suggests that MYCN and MDM2 comprise a positive feedback circuit that initiates at the onset of MYCN-driven retinoblastoma genesis." (PMID 33425720, 2020). "Based on these observations, we hypothesize that MYCNOS1 promotes oncogenesis and has functional relevance with MYCN in MYCN-amplified retinoblastoma." (PMID 33270844, 2020). "A mouse model of MYCN-amplified retinoblastoma without an RB1 mutation is generated by conditionally overexpressed MYCN in retinal cells with wildtype Rb1, but the tumors do not develop." (PMID 32824373, 2020). "High MYCN amplification is proposed as a novel mechanism of disease initiation in retinoblastoma without RB1 mutation." (PMID 32824373, 2020). "We also assessed whether ectopic MYC and MYCN induce MDM2 in a manner that is critical to the onset of tumorigenesis in an intact retina model of retinoblastoma initiation." (PMID 33425720, 2020). ",5,8MYCNOS (MYCN opposite strand) is located on the DNA strand opposite to MYCN with extensive head-to-head overlap; it is thus inevitably co-amplified in all cases of MYCN-amplified retinoblastoma." (PMID 33270844, 2020). "A very rare and aggressive subset of unilateral, non-heritable retinoblastoma can result from highly amplified MYCN in the setting of normal RB1 alleles." (PMID 31835688, 2019). "If the retinoblastoma tumor contains a MYCN amplification it may be of interest to target that gene." (PMID 29124525, 2017). "Together, findings strongly indicate the therapeutic potential of MYCN gene in retinoblastoma." (PMID 28358317, 2017). "This led to the hypothesis that high level MYCN amplification is sufficient for initiation of tumorigenesis of RB1+/+ retinoblastoma." (PMID 28211617, 2017). "However, data suggests that the transition into retinoblastoma requires further copy number changes in key genes—gain in KIF14, E2F3, MYCN and loss in DEK and CDH1." (PMID 29124525, 2017). "Conversely, rapid retinoblastoma cell death occurs when MYCN is knocked out." (PMID 28358317, 2017). "In our series, retinoblastoma cases with high MYCN copy number were associated with an earlier age of onset that was significantly different from that of retinoblastoma without MYCN amplification." (PMID 28211617, 2017). "Retinoblastoma, an embryonic neoplasm of retinal origin, was initially thought to be caused exclusively by the loss of function of the retinoblastoma (RB1) gene, but MYCN-amplification has also been reported to initiate the disease." (PMID 28358317, 2017).